KLRC4 (killer cell lectin like receptor C4)
Description:
May play a role as a receptor for the recognition of MHC class I HLA-E molecules by NK cells.
Synonyms: NKG2F; NKG2-F
Tractability: Antibody: UniProt predicts a signal peptide or a membrane-spanning region.
Gene: Protein-coding gene on chromosome 12 (10,403,059 to 10,409,757, reverse strand). Ensembl gene ENSG00000183542.
Subcellular location: Membrane
Gene Ontology:
Molecular function: activating MHC class Ib receptor activity
Biological process: natural killer cell mediated immunity; positive regulation of natural killer cell mediated cytotoxicity; stimulatory C-type lectin receptor signaling pathway
Cellular component: cell surface; plasma membrane; membrane
Genetic constraint (gnomAD): Loss-of-function variants: 7 observed, 14.45 expected, observed/expected ratio (o/e) 0.48, 90% interval 0.27 to 0.91. The upper end of that interval is the gene's LOEUF score, 0.91, which puts it in group 3 of 6, group 1 being the genes least tolerant of losing a copy. Missense variants: 137 observed, 165.59 expected, observed/expected ratio (o/e) 0.83, 90% interval 0.72 to 0.95. Synonymous variants: 44 observed, 53.81 expected, observed/expected ratio (o/e) 0.82, 90% interval 0.64 to 1.05.
Homologues: Orthologues: chimpanzee KLRC4 (96% identical), mouse Klri1 (21% identical), rat Klri1 (18% identical), rat Klri2 (18% identical), mouse Klre1 (17% identical), rat Klre1 (17% identical), mouse Klri2 (16% identical), Drosophila melanogaster rgn (15% identical), zebrafish si:ch211-170d8.8 (15% identical), zebrafish si:dkey-26c10.5 (15% identical), zebrafish si:ch211-193e13.5 (14% identical), Caenorhabditis elegans clec-146 (13% identical), and 3 more. Paralogues in human: KLRC2 (81% identical), KLRC3 (80% identical), KLRC1 (63% identical), KLRK1 (18% identical), CLEC12A (17% identical), KLRD1 (17% identical), CLEC7A (16% identical), KLRG1 (16% identical), CLEC12B (16% identical), CLEC1B (15% identical), CLEC9A (15% identical), KLRB1 (15% identical), and 11 more.
Diseases named in the same sentence as KLRC4 in open-access papers:
KLRC4 is named in the same sentence as 8 diseases in open-access papers, as found by Europe PMC text mining. Sharing a sentence is not in itself a finding about the gene and the disease. The quoted sentences say what the papers report.
epilepsy (1 paper, 2023). A brain disorder characterized by episodes of abnormally increased neuronal discharge resulting in transient episodes of sensory or motor neurological dysfunction, or psychic dysfunction. "The epilepsy-associated genes KLRC4 and NEMCE2 were high-frequency variants in all three groups." (PMID 40217327, 2023).
leukemia (1 paper, 2020). A malignant (clonal) hematologic disorder, involving hematopoietic stem cells and characterized by the presence of primitive or atypical myeloid or lymphoid cells in the bone marrow and the blood. "miR-494-3p was mainly paired with immune genes (CD3G, CXCL13, CXCR5, KLRC4), some of which had been annotated as oncogenes in leukemia including IGF1 (DRG; pan-cancer), IKZF3 (driver; leukemia), NABP1 (oncogene; leukemia), and PDGFRA (oncogene; pan-cancer)." (PMID 32605588, 2020).
preeclampsia (1 paper, 2025). Preeclampsia is a hypertensive disorder of pregnancy that is characterized by new-onset hypertension with proteinuria presenting after 20 weeks of gestation, and depending on mild or severe forms may initially present with severe headache, visual disturbances, and hyperreflexia. "Although various immune and metabolic pathways have been proposed in late-onset preeclampsia (LO-PE), direct evidence for specific processes—such as Allograft Rejection, Estrogen Response, or Glycolysis—and for genes like HLA-G, IL17RB, and KLRC4 remains limited." (PMID 40427999, 2025).
psoriasis (1 paper, 2022). An autoimmune condition characterized by red, well-delineated plaques with silvery scales that are usually on the extensor surfaces and scalp. "Some psoriasis loci showed a substantial single-tissue eQTL, primarily in the cardiovascular system (artery coronary: rs240993/KIAA1919, rs9808753/TMEM50B, heart left ventricle: rs11053802/KLRC4, heart left ventricle: rs11053802/KLRK1, rs5063/CLCN6, rs1050414/HLA-B, rs2778031/SPIN1)." (PMID 36320003, 2022).
triple-negative breast carcinoma (1 paper, 2020). An invasive breast carcinoma which is negative for expression of estrogen receptor (ER), progesterone receptor (PR), and human epidermal growth factor receptor 2 (HER2). "The same is true for BCL11B, IKZF3, and KLRC4, which have very recently been linked to a prognostic immunogenic signature of triple-negative breast cancers." (PMID 32605588, 2020).
tumor (1 paper, 2021). "High tumor expression of KLRC1 and KLRC2 were also associated with improved survival in the CGGA LGG patient cohort, but not KLRK1, KLRC2 or KLRC4." (PMID 34539622, 2021). "In contrast to TCGA LGG dataset, high tumor expression of KLRC1 and KLRC2 in CGGA LGG patients were associated with improved prognosis, but not KLRC3, KLRC4 or KLRK1." (PMID 34539622, 2021).
KLRC4 also shares sentences with these, for which no sentence is quoted: cancer (1 paper); Lupus (1).